MMP2 (matrix metallopeptidase 2)
Diseases named in the same sentence as MMP2 in open-access papers (continued):
Sharing a sentence is not in itself a finding about the gene and the disease.
tumor (continued). "In an orthotopic model of HCC in nude mice, P-5m treatment effectively reduced the lung metastasis as well as the expression of MMP-2 in the tumor tissues." (PMID 22395332, 2012). "Tumor bearing limbs of wild type mice showed a significant decrease in the trabecular bone volume compared to the MMP-2 null group by μCT and by histomorphometry." (PMID 22238668, 2012). "Given the in vivo anti-angiogenic activity of HSA/TIMP-2, we explored the regulatory effects of HSA/TIMP-2 on MMP-2, a key regulator of tumor angiogenesis known to be modulated through an interaction with TIMP-2." (PMID 22545131, 2012). "MMP-9 mRNA was expressed in cancer epithelial cells and stromal cells, while MMP-2 mRNA was predominantly expressed in tumor stromal cells." (PMID 22159401, 2012). "Matrix metalloproteinase-2 (MMP-2) is important in the dissemination and invasion of tumor cells and activates angiogenesis." (PMID 23227342, 2012). "Further the authors also revealed that Ad-MMP-2 mediated tumor growth inhibition occurred through cleavage of caspases-8,-9 and -3, and activation of FAS-mediated signaling pathway." (PMID 22962598, 2012). "Among secreted MMPs, MMP2 and MMP9 (gelatinase A and gelatinase B) are known to play a key role in tumor invasion and metastasis development." (PMID 23226772, 2012). "MMP-2 cleaved fibronectin into small fragments, which promoted the adhesion and migration of the tumor cells." (PMID 22848537, 2012). "Our results showed that inhibition of MMP-2 activity in the tumor cells dramatically decreased the adhesion and migration of the tumor cells." (PMID 22848537, 2012). "In contrast, analysis of MMP-2 expression revealed that MMP-2 was localized to both the tumor and stroma of human (n = 11) and murine osteolytic bone metastases." (PMID 22238668, 2012). "The molecular mechanism of EGCG is the result of its inhibition of urokinase and two gelatinases (MMP-2 and -9) involved in vascular as well as tumor invasion." (PMID 21977033, 2012). "IL-4 stimulation of macrophage-containing cultures resulted in enhanced tumor cell invasion evidenced by degradation of the basement membrane, enhanced collagenolytic activity and increased MMP-2 and MMP-9." (PMID 22792213, 2012). "111In-DTPA-CTT (IC50 = 1026 μM for MMP-2) was found to accumulate in tumors possessing gelatinase activity, but offered low tumor contrast." (PMID 23201642, 2012). "Apart from direct effects on tumor cells, MMP2 and VEGF are known for fostering angiogenesis and IL-8 is a major chemotactic factor for neutrophil recruitment." (PMID 22171994, 2011). "Intriguingly MMP-2 has been shown to dock on tumor cell-surface integrins, which makes gelatinases even more interesting as a target." (PMID 21490745, 2011). "NDRG2 antagonizes transforming growth factor-β1 (TGF-β1)-mediated tumor cell invasion by down-regulating the expression of matrix metalloproteinase 2 (MMP2), plasminogen activator inhibitor type 1 (PAI-1) and Rho GTPase activity." (PMID 21676268, 2011). "Only MMP-2 activity was clearly detected in extracts from tumor-bearing brains, and it was higher than in extracts from tumor-free brains." (PMID 21901144, 2011). "This marked increase in MMPs in the malignant group was expected since MMP2 is synthesized by tumor cells or quite commonly by host response to tumor as in fibroblasts, macrophages, and vascular endothelial cells." (PMID 21483670, 2011). "The interaction between fibronectin and tumour cells activates various signalling pathways involved in tumour progression, leading for example to the increased expression of metalloproteinases MMP-2 and -9." (PMID 21426571, 2011). "In vivo studies utilizing Maspin expression vectors showed a significant decrease in melanoma tumor growth and experimental lung metastasis as well as decreased MMP-2, VEGF, and Maspin expression levels from tumor sections." (PMID 21378407, 2011).
tumor (continued). "Given the role of survivin, VEGF, and MMP2 in tumor cell survival, angiogenesis, and metastasis, we determined if downregulation of STAT3 DNA binding correlated with loss of expression of these STAT3 transcriptional targets in OSA cell lines." (PMID 21443800, 2011). "Overexpression of MMP2 and MMP9 has been frequently detected in solid tumors and associated with tumor invasion and metastasis, including HCC." (PMID 21760911, 2011). "For each tumor sample, the active and inactive forms of MMP2 and MMP-9 were measured by their gelatinolytic activities." (PMID 21726449, 2011). "The initial step of tumor cell invasion is characterized by the breakdown of the base membrane, a process known to be dependent on type IV collagen-degrading enzymes, mainly MMP-2 and MMP-9." (PMID 21955589, 2011). "In the present study, we performed in vitro and in vivo experiments to analyze the effects of TGZ on tumor growth and pulmonary metastasis development of LM 8 cells, as well as on the expression of MMP-2 and VEGF." (PMID 20170548, 2010). "Our data revealed that both tumor MMP2 activity (Figure 4A1) and MMP2 (Figure 4A2) and VEGF protein levels were significantly down-regulated in treatment groups, whereas TIMP2 levels were up-regulated when compared to the controls." (PMID 20969807, 2010). "It is this event that represents an important stage of tumor progression and is demonstrated principally by a coexpression of MMP-2 and MMP-9 in invasive and in situ melanoma." (PMID 20585601, 2010). "Another derivate, galloyl glucose, blocked HT-1080 tumour invasion through gelatin by inhibiting matrix metalloprotease-2 (MMP-2) and MMP-9." (PMID 20424615, 2010). "The expression and activity of MMP-2 within the tumor of the TGZ group were lower than those of the control group." (PMID 20170548, 2010). "Other investigators have demonstrated that knockdown of OPN decreases the expression of PI3'-kinase, JNK1/2, Src and Akt, uPA, MMP-2 and -9 in various tumor cell lines." (PMID 20849637, 2010). "Treatment of tumor-bearing mice with TGZ decreases the expression and activity of MMP-2 within the tumor, and inhibits primary tumor growth and pulmonary metastasis development." (PMID 20170548, 2010). "Since MMP-2 is known to play a significant role in the invasive property of tumor cells, we investigated the mechanism behind the delay in wound healing exhibited by ACE-c treated cells." (PMID 20482751, 2010). "In summary, proteolytic enzymes MMP9, MMP2 and macrophages in stroma contribute to GC progression by facilitating tumor angiogenesis." (PMID 20950454, 2010). "Activation of proMMP-2 by MT1-MMP is considered to be a pivotal step in tumor cell invasion, as activated MMP-2 degrades collagen type IV and laminin, the major components of basement membranes." (PMID 21179238, 2010). "We discovered that extracellular hsp90α acts in tumor cell invasion through its activation of the pro-invasive protein matrix metalloproteinase-2 (MMP-2)." (PMID 20553606, 2010). "The resulting tumours were characterized by increased development of extracellular matrix, as well as an increase of murine S100A4 concentration and activity of MMP-2 in the tumour interstitial fluid." (PMID 20723242, 2010). "The promotion of tumor invasion and metastasis has been reported in mice deficient in TNX through the activation of the matrix metalloproteinase 2 (MMP2) and MMP9 genes." (PMID 20969748, 2010). "In particular, MMP-2 and -9, which are called gelatinases, are key enzymes for degrading type IV collagen and are thought to play critical roles in tumor invasion and metastasis." (PMID 20631911, 2010). "MMP-2 was upregulated in co-injection tumours, demonstrated by zymography, Western blot, and cytokine array analysis of TIF." (PMID 20723242, 2010). "The expression and activity of matrix metalloproteinase 2 (MMP-2) within the tumor were determined by immunohistochemistry and zymography." (PMID 20170548, 2010).
tumor (continued). "MMP-2 and -9 play an important role in cell-matrix interaction and tumor invasion in PCa and Wnt signaling has been reported to regulate the expression of MMPs." (PMID 20573255, 2010). "As increased production of MMP2 and MMP9 is associated with tumour invasion, we examined the capacity of G3F cells to produce the enzymes that are implicated in the breakdown of basement membrane by invading tumour cells." (PMID 20197768, 2010). "Quantification of the intensity of the MMP-2-specific bands showed increased activity of MMP-2 in TIFs isolated from MCF7S1 + HMF3s tumours." (PMID 20723242, 2010). "The presence of active MMP-2 and -9 in the tumor results in alterations to the microenvironment that promote tumor invasion and metastasis." (PMID 20170548, 2010). "MMP-2 secreted by normal and tumor cells has been shown to play a key role in angiogenesis, tumor cell invasion, and metastasis, by promoting degradation of Extracellular Matrix (ECM) and cleavage of cytokines, growth factors, hormones, and cell receptors." (PMID 20689590, 2010). "Matrix metalloproteinase-2 (MMP-2) promotes tumor invasion and progression by destroying the extracellular matrix (ECM) and basement membrane." (PMID 19995435, 2009). "Since MMP-2 and MMP-9 play a critical role in tumor cell invasiveness, we examined the effect of risedronate on the enzyme activities of MMP-2 and MMP-9." (PMID 19624845, 2009). "It has previously been shown that expression changes in the angiogenesis related genes bFGF, VEGF, and MMP-2 are closely related to tumor growth and metastasis." (PMID 19671184, 2009). "gene (Mmp2) is involved in tissueremodeling and tumor progression and is related to a family of human matrixmetalloproteinases." (PMID 20157509, 2009). "It has recently been shown that matrix metalloproteinase (MMP)-2 secreted by tumour cells degrades vitronectin and produces fragmented vitronectin, which is more potent than its naïve form in promoting adhesion and migration of cancer cells." (PMID 19400944, 2009). "Using a TMA comprising benign and tumor samples from 448 patients, we showed an inverse correlation between cystatin C and MMP2 expression." (PMID 19956729, 2009). "MMP-2 is one of the most important proteolytic enzymes that degrade basement membrane and extracellular matrix during tumor invasion and metastasis." (PMID 19995435, 2009). "Increased expression and activity of MMP-2 and -9 in tumors leads to the degradation of basement membranes, an essential step in tumor invasion." (PMID 19531263, 2009). "To explore the activity of sorafenib on the effectors involved in tumour progression and angiogenesis, we measured MMP2 and VEGF production in supernatants of all the 7 cell lines tested." (PMID 20003259, 2009). "STAT3 is known to regulate the transcription of MMP2, a matrix metalloproteinase known to be important in tumor cell migration and metastasis." (PMID 19284568, 2009). "Based on these experiments, we suggest that PTTG1 is actively involved in tumor angiogenesis and metastasis via activation of proteolysis and increases in invasion occur through modulation of MMP-2 activity and its expression." (PMID 19014669, 2008). "For the survival analysis, an optimised cutoff point value was identified for the tumour MMP-2 level (18.5 ng per mg protein, LR 5.07, P=0.024)." (PMID 18506186, 2008). "Our data showed that CAS was localized in vesicle and CAS overexpression enhanced the secretion of MMP-2 and enhanced the invasion and metastasis of tumour cells." (PMID 18597698, 2008). "The cutoff point analysis showed a broad range of MMP-2 levels with a significant and unidirectional relation with survival outcome: high tumour MMP-2 levels are unfavourable for the patients' prognosis." (PMID 18506186, 2008).
tumor (continued). "This focal expression of Mmp13 in the tumor core was very different from the expression of Mmp2 and Mmp14, which were found throughout the tumor stroma, including at the tumor periphery, and in areas with hyperplasia, grade I and grade II MIN (not shown)." (PMID 18698413, 2008). "Endothelial cells constitutively secrete MMP-2, which is required for the tumour to trigger the angiogenic response." (PMID 18782185, 2008). "This is the first demonstration of a direct rescue of impaired cell invasion by the re-expression of MMP-2 in a tumour cell type with decreased expression of functional FAK." (PMID 18349846, 2008). "At the same time, tumor cells secrete MMP-2 and MMP-9 that degrade the matrix around the tumor and the nerve tissue, promoting PNI." (PMID 18983683, 2008). "We can see clearly from the previous results that tumor-mesothelial cells adhesion up-regulate MMP-2 and MMP-9 expression." (PMID 19662219, 2007). "For example, tumor cells and tumor-associated macrophages are known to secrete matrix metalloproteinases, such as MMP-9 and MMP-2." (PMID 18042290, 2007). "Overexpression of MMP-1, MMP-2, and MMP-3 has been linked to poor prognosis, high tumour stage, and enhanced tumour invasiveness in patients with CRC." (PMID 17311017, 2007). "Mesothelial cells showed constitutive expression of MMP-2, no significant up-regulation was observed when they were allowed indirect contact with tumor cells, however, noticeable increase in MMP-2 activity occurred when direct contact was initiated, P = 0.05." (PMID 19662219, 2007). "The MMP2 and MMP3 transcriptionally more active polymorphisms appear more frequently among individuals with many moles, tumor infiltrating lymphocytes, and low Clark level, and the number of alleles seems associated with absence of ulceration." (PMID 17958893, 2007). "Levels of both PTTG and MMP-2 are reported to correlate with the angiogenesis and metastasis of tumor, suggesting for a existence of relationship between PTTG and MMP-2." (PMID 17096843, 2006). "To determine the role of PTTG on invasion and migration of tumor cells through MMP-2, we used stably transfected HEK293 cells." (PMID 17096843, 2006). "Membrane type-1 (MT1) MMP specifically activates the pro-gelatinase, MMP-2 on tumor cell surface in vitro and binds with tissue inhibitor of matrixproteinases (TIMPs), hence, controlling MMP-2 activity." (PMID 17096843, 2006). "Multiple MMPs are involved in the degradation of the surrounding matrix, but MMP-2 has been at the forefront in tumor invasion, angiogenesis, and metastases." (PMID 17096843, 2006). "Extracellular MMP inducer expression was compared with clinicopathological parameters of tumours, including levels of ki-67, MMP-2, MMP-9 and vascular endothelial growth factor (VEGF), MVD as well as survival time of carcinoma patients." (PMID 17088917, 2006). "MMP-2 null fibroblast invasion was comparable to wild-type in the absence of tumor cells, but MMP-2 deficient fibroblasts cocultured with FaDu tumor cells decreased in vitro invasion by almost 50%." (PMID 16515711, 2006). "Tumor and stromal cells express high levels of MMP-2, which allows the cells to invade and metastasize." (PMID 17096843, 2006). "MMP-2 plays a role in various tissue remodelling processes, including trophoblast invasion and tumour cell motility." (PMID 17137503, 2006). "When tumour cells are introduced into MMP2 knockout mice, the tumours that develop are less vascularized and exhibit reduced growth compared to the tumours in wild-type animals." (PMID 17026740, 2006). "Here we report changes in tumor phenotype when FaDu HNSCCs cells are cocultured with WT, MMP-2 null, MMP-9 null or MT1-MMP null fibroblasts in vitro and in vivo." (PMID 16515711, 2006). "Previous studies have implicated other MMPs (i.e. MMP-2 and MMP-9) in tumor cell invasion and progression, and that LPA triggers upregulation or activation of MMP-2." (PMID 17156449, 2006).
tumor (continued). "CHL inhibited U-87 cell migration and matrix metalloproteinase (MMP)-2 secretion, two prerequisites for tumor cell invasion." (PMID 16566826, 2006). "The invasive potential of HNSCC tumor cells were assessed in vitro atop type I collagen gels in coculture with wild-type (WT), MMP-2 null, MMP-9 null or MT1-MMP null fibroblasts." (PMID 16515711, 2006). "In this study, MMP-2 was confirmed as being very highly expressed in tumour tissue, and to correlate significantly with increasing tumour grade." (PMID 16465195, 2006). "The matrix metalloproteinases (MMPs) including MMP-2 degrade basement membranes and stromal extracellular matrix, resulting in tumour invasion and metastasis." (PMID 17133272, 2006). "In this study the diagnostic performance criteria sensitivity, specificity, and ROC data revealed the best values for MMP2 as a separate tumour marker for TCC." (PMID 16901349, 2006). "Animal studies showed that carcinoma cell lines transfected with MMP-14 produced higher levels of active MMP-2 and developed more lung metastases compared to parent tumor cells." (PMID 16776850, 2006). "The reduced influence of MMP-2 null fibroblasts on FaDu tumor invasion in vitro and growth in vivo (49% less tumor volume) remained consistent." (PMID 16515711, 2006). "MMP-2 is increased in cancer tissue and its over-expression is correlated with tumour-related basement membrane degradation and vascular invasion." (PMID 15740610, 2005). "Our previous screen identified an extracellular role for Hsp90 in regulating tumor cell invasion through regulation of MMP2 activity." (PMID 15471548, 2004). "Nonetheless, the positive correlation between MMP-2 activity and nodal status noted here is in keeping with a number of studies in other tumours cited above." (PMID 12771921, 2003). "The ratio of circulating MMP-2/TIMP-1 was also significantly higher in episodes of tumour control vs tumour progression and prior to treatment (P⩽0.0001)." (PMID 12698191, 2003). "Infiltration of tumour cells from the blood vessels and invasion into metastatic organs are regulated by MMPs such as MMP-2 and MT1-MMP produced by host cells as well as tumour cells." (PMID 12698202, 2003). "This study demonstrates the consistent expression of active and latent forms of MMP-9 and particularly MMP-2 in MM tumour samples by gelatin zymography." (PMID 12771921, 2003). "In grade 2 and 3, tumours MMP-2 positivity correlated significantly with shortened overall survival (P=0.04)." (PMID 14520459, 2003). "Matrix metalloproteinases (MMPs), in particular the gelatinases (MMP-2 and -9), play a significant role in tumour invasion and angiogenesis." (PMID 12771921, 2003). "Comparing the MMP activity with stage of disease, a trend was observed towards lower levels of active MMP-2 and proMMP-2 with advanced stage of disease in tumour (P=0.024 and P=0.044 respectively) and in normal mucosa (P=0.019 and NS respectively)." (PMID 12085179, 2002). "For MMP-2 this ratio increased five-fold (P<0.001) in tumour tissue and four-fold (P<0.001) in transitional tissue, as compared to normal mucosa." (PMID 12085179, 2002). "A cell membrane-bound metalloproteinase (MT1-MMP), present on tumour cells, has been shown to activate proMMP-2 and is most likely responsible for anchoring MMP-2 to these malignant cells." (PMID 12085179, 2002). "The active to proform ratio of MMP-2 is highest in tumour tissue, whereas this ratio for MMP-9 is highest in distant normal mucosa." (PMID 12085179, 2002). "The absolute activity of these MMP-2 levels in normal mucosa were, however, much lower (approximately 10 times) than those in tumour tissue." (PMID 12085179, 2002). "This also applied to the MMP-2 active to proenzyme ratio in tumour (P=0.028) and normal mucosa (P=0.002)." (PMID 12085179, 2002).